G6PC1 (glucose-6-phosphatase catalytic subunit 1)
Description:
Hydrolyzes glucose-6-phosphate to glucose in the endoplasmic reticulum. Forms with the glucose-6-phosphate transporter (SLC37A4/G6PT) the complex responsible for glucose production in the terminal step of glycogenolysis and gluconeogenesis. Hence, it is the key enzyme in homeostatic regulation of blood glucose levels.
Synonyms: G6Pase; G6PC; G6PT; GSD1a; GSD1
Tractability: Small molecule: a structure with a bound ligand is known; it belongs to a druggable protein family. Antibody: UniProt predicts a signal peptide or a membrane-spanning region. PROTAC: a small molecule that binds it is known.
Target class: Enzyme; Phosphatase
Gene: Protein-coding gene on chromosome 17 (42,900,797 to 42,914,438, forward strand). Ensembl gene ENSG00000131482.
Subcellular location: Endoplasmic reticulum membrane
Subcellular location (Human Protein Atlas): Mid piece
Pathways (Reactome):
Chromatin organization: Interaction of NuRD complexes with transcription factors
Disease: Glycogen storage disease type Ia (G6PC)
Gene expression (Transcription): FOXO-mediated transcription of oxidative stress, metabolic and neuronal genes
Metabolism: Gluconeogenesis
Gene Ontology:
Molecular function: glucose-6-phosphatase activity; phosphate ion binding; protein binding; phosphotransferase activity, alcohol group as acceptor
Biological process: gluconeogenesis; glucose homeostasis; glucose 6-phosphate metabolic process; glycogen metabolic process; cellular response to insulin stimulus; chemical homeostasis; lipid homeostasis; response to carbohydrate; response to food; response to insulin; response to nutrient levels; response to resveratrol
Cellular component: membrane; endoplasmic reticulum membrane; endoplasmic reticulum
Genetic constraint (gnomAD): Loss-of-function variants: 20 observed, 30.18 expected, observed/expected ratio (o/e) 0.66, 90% interval 0.47 to 0.96. The upper end of that interval is the gene's LOEUF score, 0.96, which puts it in group 4 of 6, group 1 being the genes least tolerant of losing a copy. Missense variants: 375 observed, 442.57 expected, observed/expected ratio (o/e) 0.85, 90% interval 0.78 to 0.92. Synonymous variants: 160 observed, 182.19 expected, observed/expected ratio (o/e) 0.88, 90% interval 0.77 to 1.
Gene-disease validity (ClinGen):
ClinGen rates the evidence that G6PC1 causes each of these diseases.
glycogen storage disease I (autosomal recessive): Definitive.
Homologues: Orthologues: chimpanzee G6PC1 (99% identical), macaque G6PC1 (98% identical), dog G6PC1 (92% identical), pig G6PC1 (92% identical), rabbit G6PC1 (89% identical), mouse G6pc1 (89% identical), rat Psme3 (87% identical), guinea pig G6PC1 (84% identical), tropical clawed frog g6pc1 (69% identical), tropical clawed frog g6pc1.3 (65% identical), tropical clawed frog g6pc1.2 (64% identical), zebrafish g6pc1a.2 (64% identical), and 2 more. Paralogues in human: G6PC2 (50% identical), G6PC3 (33% identical).
Diseases named in the same sentence as G6PC1 in open-access papers:
G6PC1 is named in the same sentence as 132 diseases in open-access papers, as found by Europe PMC text mining. Sharing a sentence is not in itself a finding about the gene and the disease. The quoted sentences say what the papers report.
Hyperglycemia (120 papers, 2007 to 2026). An increased concentration of glucose in the blood. "Insulin fails to suppress the expression of Pepck and G6pc1 mRNA during the refeeding period, leading to greater glucose release into circulation, resulting in hyperglycemia." (PMID 40507838, 2025).
diabetes (80 papers, 2011 to 2026). "Consistent with its metabolic function, dysregulation of G6PC1 gene expression contributes to diabetes, and mutations that impair phosphohydrolase activity form the clinical basis of glycogen storage disease type 1a." (PMID 34952005, 2022). "Nonetheless, the question remains as to why monocytes were not increased as a consequence of the increased epinephrine in mice with hepatocyte-specific G6pc1 deficiency, similar to effects of insulin injections in patients with diabetes." (PMID 34091064, 2021). "Consequently, an increase of G6PC1 activity has been implicated in the pathology of diabetes by driving hepatic glucose production, a major contributor to hyperglycemia." (PMID 34952005, 2022). "Thus, we propose that G6PC1 may contribute to the metabolic disorders associated with diabetes and obesity, potentially influenced by fructose metabolism." (PMID 40664655, 2025).
Hypoglycemia (67 papers, 2009 to 2025). A decreased concentration of glucose in the blood. "Logically, G6PT deficiency causes the same metabolic symptoms (hepatorenal glycogenosis, lactic acidosis, hypoglycemia) as deficiency in G6PC1 (GSD1a)." (PMID 37238286, 2023). "Similar to previous data, hepatocyte-specific G6pc1 deficiency induced hypoglycemia (blood glucose ≤4.0 mM) upon a 6 h fasting period." (PMID 35782606, 2022). "•Fasting-induced hypoglycemia in hepatocyte-specific G6pc1 deficiency disturbs platelet aggregation." (PMID 34091064, 2021). "We then assessed where myeloid cells would accumulate during fasting-induced hypoglycemia in hepatocyte-specific G6pc1 deficiency." (PMID 34091064, 2021). "•Fasting-induced hypoglycemia in hepatocyte-specific G6pc1 deficiency increases plasma corticosterone." (PMID 34091064, 2021). "A recent study has revealed that hypoglycemia in hepatocyte-specific G6pc1 deficient mice impairs very-low-density lipoprotein (VLDL) catabolism, which was suggested to be caused by decreased lipoprotein lipase (LPL) activity." (PMID 34091064, 2021). "We further investigated the mechanism underlying the decrease in blood Ly6Chi monocytes and their accumulation in bone marrow upon fasting-induced hypoglycemia in hepatocyte-specific G6pc1 deficiency." (PMID 34091064, 2021). "We first confirmed that similar to previous studies, hepatocyte-specific G6pc1 deficiency induces hypoglycemia after a fasting period of 6 h." (PMID 34091064, 2021). "Our studies showed that fasting-induced hypoglycemia in hepatocyte-specific G6pc1 deficiency increases plasma levels of both corticosterone and epinephrine, and the decrease in blood monocytes suggests that the effect of corticosterone is predominant." (PMID 34091064, 2021). "The increase in plasma cortisol in the fed state does not exclude that GSD Ia patients might exhibit high cortisol levels upon fasting-induced hypoglycemia, similar to mice with hepatocyte-specific G6pc1 deficiency." (PMID 34091064, 2021). "•Fasting-induced hypoglycemia in hepatocyte-specific G6pc1 deficiency decreases blood monocytes." (PMID 34091064, 2021). "In addition, we found that hepatocyte-specific G6pc1 deficiency disturbs platelet aggregation during fasting-induced hypoglycemia, accounting for the bleeding phenotype in GSD Ia." (PMID 34091064, 2021). "Currently, gene therapies targeting G6PC1 have shown the potential to correct hypoglycemia and prevent other metabolic disorders in GSD-1a animal models and in a clinical trial (ClinicalTrials.gov Identifier: NCT03517085)." (PMID 40664655, 2025). "In addition to hypoglycaemia and reduced hepatic G6pc1 expression, hepatic glycogen stores, an additional source for hepatic glucose output, tended to be reduced in fasted Atp8b1 mutant mice compared to WT mice." (PMID 40851490, 2025). "Together with our results in mice with hepatocyte-specific G6pc1 deficiency, these findings indicate that disturbed platelet aggregation in GSD Ia is the consequence of low levels of ATP and ADP in the platelet dense granules due to hypoglycemia." (PMID 34091064, 2021). "We did not detect differences in plasma MCP-1 upon fasting-induced hypoglycemia in hepatocyte-specific G6pc1 deficiency, but we did observe an increase in plasma corticosterone and epinephrine." (PMID 34091064, 2021). "In support of this notion, mice lacking hepatic g6pc1 develop lethal hypoglycemia in response to polymicrobial sepsis or heme administration." (PMID 30425714, 2018).
type 2 diabetes (49 papers, 2012 to 2025). "Moreover, G6PC1 mRNA and glucose-6-phosphatase activity are elevated in animal models of both type 1 and type 2 diabetes." (PMID 34952005, 2022).
glycogen storage disease type Ia (45 papers, 2012 to 2026).
glycogen storage disease (32 papers, 2012 to 2026). "Supporting this hypothesis is the observation that of the 56 AAs in human G6PC1 mutation of which gives rise to glycogen storage disease (GSD) type 1a, 51 are conserved or represent conserved changes in human G6PC2." (PMID 27611587, 2016). "Bi-allelic G6PC1 mutations cause type 1a glycogen storage disease (GSD1a, MIM 232200)." (PMID 23758768, 2013).
Glycogen storage disease type I (24 papers, 2011 to 2024). "Mutations of G6PC1 or G6PT cause glycogen storage disease type I and result in impaired hepatic regulation of glucose homeostasis." (PMID 31582762, 2019).
steatosis (14 papers, 2014 to 2025). Increased lipid within the cytoplasm of cells. "Delivering functional G6PC1 may ameliorate steatosis in patients with deficiency." (PMID 40065360, 2025). "In total, we identified 27 genes, of which 3 are monogenic causes of steatosis (APOB, G6PC1, PPARG), 4 were previously associated with MASLD (APOB, APOC3, INSR, PPARG), and 23 had supporting clinical, experimental, and/or genetic evidence." (PMID 40065360, 2025).
liver cancer (12 papers, 2016 to 2025). An epithelial or non-epithelial malignant neoplasm that arises from the liver. "Pan-cancer analysis indicated that G6PC1 was significantly downregulated in most cancer types, such as liver cancer, bile duct cancer, colon cancer, kidney clear cell carcinoma, kidney papillary cell carcinoma, and kidney chromophobe." (PMID 40821770, 2025).
glioblastoma (10 papers, 2015 to 2025). The most malignant astrocytic tumor (WHO grade IV). "In several malignancies originating from non-gluconeogenic organs, such as glioblastoma, ovarian cancer, gastric cancer, and cervical carcinoma, elevated G6PC1 expression has been detected and is associated with enhanced tumor aggressiveness and metastatic potential." (PMID 40821770, 2025).
hepatocellular adenoma (10 papers, 2013 to 2026). A benign epithelial neoplasm arising from the hepatocytes.
clear cell renal cell carcinoma (6 papers, 2020 to 2025). "In addition, other studies have reported miRNA-mediated deregulation of G6PC1 expression in HCC and its reduced expression in different gluconeogenic tumor tissues, such as clear cell renal cell carcinoma." (PMID 40821770, 2025).
ovarian carcinoma (5 papers, 2019 to 2025). A malignant neoplasm originating from the surface ovarian epithelium. "Some studies have reported that G6PC1 is highly expressed in ovarian cancer, where it is significantly associated with short-term recurrence and poor prognosis." (PMID 40821770, 2025). "Dysregulation in the global G6Pase system has been implicated in various cancers, including ovarian cancer and HCC, but the specific contributions of the G6PC1-3 and SLC37A1-4 isoforms remains unclear." (PMID 38034009, 2023).
glucose metabolism disorder (3 papers, 2021 to 2025). "The key role of G6PC1 in maintaining glucose homeostasis makes it a focal point for developing new treatments for glucose metabolic disorders, particularly those involving impaired glucose regulation." (PMID 40664655, 2025).
neutropenia (3 papers, 2020 to 2023). A decrease in the number of neutrophils found in the blood. "Its deficiency results in Glycogen Storage Disease type Ib,21, 22 which combines the same metabolic symptoms as G6PC1 deficiency with a severe neutropenia similar to that observed in G6PC3 deficiency." (PMID 31691304, 2020).
renal cell carcinoma (3 papers, 2020 to 2025). "Conversely, in cancers arising from gluconeogenic tissues, including HCC and renal cell carcinoma, G6PC1 expression is frequently suppressed, correlating with poorer clinical outcomes." (PMID 40821770, 2025).
brain tumor (2 papers, 2023 to 2024). "Total RNA was extracted and gene expression of G6PC1-3 as well as of SLC37A1-4 members analyzed by qPCR in four human brain cancer cell lines and from clinically annotated brain tumor cDNA arrays." (PMID 38034009, 2023).
carbohydrate metabolism disorder (2 papers, 2024 to 2025).
tumor (48 papers, 2007 to 2025). "The results offer crucial insights into identifying G6PC1 as a tumor suppressor, highlighting its close association with immunity and metabolism." (PMID 40821770, 2025). "Associations between G6PC1 and HCC metabolic reprogramming, as well as the tumor microenvironment were analyzed." (PMID 40821770, 2025). "Overall, our findings suggest that HCC patients with lower G6PC1 expression exhibit enhanced tumor immune suppression, implying potential responsiveness to immunotherapy." (PMID 40821770, 2025). "G6PC1 is abnormally expressed in various cancer types, contributing to metabolic reprogramming, proliferation, invasion, and metastasis of tumor cells." (PMID 40821770, 2025). "In a comparison of 50 pairs of HCC and adjacent non-tumor tissues, a significant reduction in G6PC1 expression was observed in the HCC tissues." (PMID 40821770, 2025). "The results revealed that consistent downregulation of G6PC1 across multiple tumor types, with its reduced expression correlating significantly with adverse clinical outcomes." (PMID 40821770, 2025). "In this study, we innovatively integrated multi-omics analysis with experimental validation to identify G6PC1 as a potential tumor suppressor and prognostic biomarker for HCC." (PMID 40821770, 2025). "The results showed that the IHC staining intensity of G6PC1 was significantly lower in HCC tissues than in adjacent non-tumor tissues." (PMID 40821770, 2025). "G6PC1 exhibited higher expression in the normal tissue compared to the tumor, stromal, and immune regions in all three HCC patients." (PMID 40821770, 2025). "Initially, we assessed the expression levels of G6PC1 in tumor and control samples using TIMER2.0." (PMID 40821770, 2025). "Patients with higher tumor grade and advanced T stage exhibited lower G6PC1 expression." (PMID 40821770, 2025). "Notably, G6PC1 was expressed at low levels in malignant cells at the single-cell transcriptome level and in the tumor region at the spatial transcriptome level within the HCC TME, suggesting a potential association between G6PC1 and HCC malignancy." (PMID 40821770, 2025). "Although previous studies have reported G6PC1 deregulation in HCC and its role in liver metabolism, the impact of G6PC1 on HCC prognosis, as well as its functional significance in the tumor immune microenvironment and metabolic reprogramming, remains unclear." (PMID 40821770, 2025). "Overall, we utilized multi-omics datasets from the GEO, TCGA, HCCDB, TISCH, and HPA databases to comprehensively explore the impact of G6PC1 on HCC prognosis, metabolic reprogramming, tumor immune microenvironment, drug sensitivity, and immunotherapy potential." (PMID 40821770, 2025).
cancer (36 papers, 2014 to 2026). A tumor composed of atypical neoplastic, often pleomorphic cells that invade other tissues. "G6PC1 (Glucose‐6‐Phosphatase Catalytic Subunit 1) is abnormally expressed in various cancers, including HCC." (PMID 40821770, 2025). "Among the 850 hypoxia-related genes, 6 genes (LOC101928143, LOC102723407, MIR1281, PLA2G4B, SLC5A10, and G6PC1) were absent from the TCGA pan-cancer RNA-seq data; thus, 844 genes with RNA expression values were used in the analysis." (PMID 38248716, 2023).
metabolic disorder (35 papers, 2010 to 2025). "Glycogen storage disease type 1a (GSD Ia) is a rare inherited metabolic disorder caused by mutations in the glucose-6-phosphatase (G6PC1) gene." (PMID 34091064, 2021). "While its role in metabolic disease makes G6PC1 an attractive therapeutic target, the conspicuous absence of efficient heterologous expression and purification methodologies precludes a detailed molecular understanding of its structure and function." (PMID 34952005, 2022). "The methodologies described here overcome long-standing obstacles in the field and lay the necessary groundwork for a detailed analysis of the mechanistic structural biology of G6PC1 and its role in complex metabolic disorders." (PMID 34952005, 2022). "G6Pase enzyme is encoded by G6PC1, G6PC2, and G6PC3 genes which are responsible for metabolic disorders." (PMID 27051561, 2016).
infection (10 papers, 2011 to 2025). The state of being infected such as from the introduction of a foreign agent such as serum, vaccine, antigenic substance or organism. "Furthermore, gene expression analysis showed a significant upregulation of key gluconeogenic enzymes, including glucose-6-phosphatase catalytic (G6Pc1) and phosphoenolpyruvate carboxykinase (PCK2), in SFTSV-infected Huh7 cells at 48 hours post-infection (hpi) compared to mock controls." (PMID 40391966, 2025).
G6PC1 also shares sentences with these, for which no sentence is quoted: Insulin resistance (114 papers); hepatoma (44); Obesity (26); Hepatic steatosis (23); Glucose intolerance (18); Hyperinsulinemia (11); hyperlipidemia (9); hyperuricemia (9); dyslipidemia (8); genetic disease (7); hypertriglyceridemia (7); liver disease (7); kidney disease (6); Sepsis (6); type 1 diabetic (6); adenoma (5); lactic acidosis (5); nephromegaly (5); breast carcinoma (4); glycogen storage disease Ib (4); Impaired glucose tolerance (4); Cerebral ischemia (3); cervical carcinoma (3); Cirrhosis (3); Nephropathy (3); triple-negative breast carcinoma (3); atherosclerosis (2); Autoimmunity (2); colon carcinoma (2); Crohn disease (2).
A further 80 diseases each share a sentence with G6PC1 in 2 papers or fewer.